INSR (insulin receptor)
Diseases named in the same sentence as INSR in open-access papers (continued):
Sharing a sentence is not in itself a finding about the gene and the disease.
Hepatic steatosis (33 papers, 2013 to 2026). Steatosis is a term used to denote lipid accumulation within hepatocytes. "Impaired insulin sensitivity disrupts the balance of glucose and lipid metabolism, increasing the risk of hepatic steatosis, and trivalent Cr, as a co-factor to activate the insulin receptor, improves insulin action in insulin-sensitive tissues, such as adipose, skeletal muscle, liver tissue, etc.." (PMID 38721033, 2024). "A study revealed that by inhibiting Ptpn1 expression and promoting phosphorylation of insulin receptor, microRNA-206 impaired hepatic lipogenesis and exerted the beneficial effect of preventing hepatic steatosis." (PMID 37033250, 2023). "Further, more clarity is needed to define the structural changes in the IR in an insulin-resistant state and to determine if activation of the insulin receptor is necessary for lipogenesis in NAFLD after the onset of fatty liver disease." (PMID 37242206, 2023). "Here the authors report that mice with partially reduced insulin receptor expression in peripheral tissues are protected from and experience reversal of fatty liver disease." (PMID 32350271, 2020). "In human liver tumors, increased expression of YAP is associated with high levels of p-AKT, and recent study has showed that Hippo pathway prevented hepatic steatosis and liver tumors by suppressing the insulin receptor substrate (IRS)/AKT signaling." (PMID 31142342, 2019). "Hepatic steatosis has, in turn, been shown to exacerbate insulin resistance by interfering with the phosphorylation of insulin receptor substrates, with the amount of hepatic steatosis correlating with the severity of IR." (PMID 27314342, 2016). "Further mechanistic studies revealed that Dyrk1b spontaneously causes fatty liver in rodents by increasing de novo lipogenesis and hepatic fatty acid uptake, despite suppressing the canonical insulin signaling by PKC epsilon-mediated insulin receptor inactivation." (PMID 37242206, 2023).
atherosclerosis (29 papers, 2011 to 2025). A disease characterized by the build-up of fatty material and calcium deposition in the arterial wall resulting in partial or complete occlusion of the arterial lumen. "In contrast, a potentially more conservative pharmacological approach using a Nox2-specific inhibitor slows the progression of atherosclerosis in mice haploinsufficient for the insulin receptor, and deficient in Apolipoprotein E." (PMID 39401163, 2024). "Here, we report the following key findings: i) whole-body haploinsufficiency of the insulin receptor in Apolipoprotein E (ApoE) deficient mice leads to accelerated atherosclerosis in the thoracoabdominal aorta and at the level of the aortic sinus." (PMID 39401163, 2024). "INSR, encode insulin receptor that are responsible for accelerated atherosclerosis within vascular smooth muscle cells in diabetic patients." (PMID 37943808, 2023). "In mice, deletion of the insulin receptor (IR) from vascular endothelial cells in the apolipoprotein-E-deficient mice (ApoE−/−) leads to an increased rate of atherosclerosis development." (PMID 28752048, 2017). "Complete loss of insulin signal in vascular endothelial cells aggravated atherosclerosis in endothelium-specific insulin receptor–deficient apolipoprotein E null mice." (PMID 24349318, 2013). "In the present report, we demonstrate that mice haploinsufficient for the insulin receptor, and deficient in Apolipoprotein E develop accelerated atherosclerosis, showing for the first time that insulin resistance at a whole body level drives the development of atherosclerosis." (PMID 39401163, 2024). "Moreover, we demonstrate that genetic deficiency of the superoxide-generating enzyme Nox2 NADPH oxidase in mice haploinsufficient for the insulin receptor, and deficient in Apolipoprotein E leads to accelerated atherosclerosis and significant disruption of the architecture of the arterial wall." (PMID 39401163, 2024). "Mouse-specific atherosclerosis mechanisms identified in the aorta include signaling by insulin receptor, EGFR, ERBB2, NGF, and TGF-beta signaling, axon guidance, VEGF and VEGFR pathways, and Tap63 and DeltaNp63 pathways." (PMID 38060277, 2023). "deletion of the insulin receptor in macrophages results in decreased atherosclerosis and inflammatory cytokine production by macrophages, despite identical blood lipoprotein levels and metabolic features." (PMID 26847458, 2016). "In contrast, hepatic insulin receptor deletion promotes atherosclerosis even in wild type mice, due to the development of “selective” insulin resistance." (PMID 26847458, 2016). "Unlike the present report in studies of mice with haploinsufficiency of the insulin receptor on an Apolipoprotein-deficient background, Rask-Madsen and colleagues did not demonstrate accelerated atherosclerosis using a similar model." (PMID 39401163, 2024). "Furthermore, IR can promote the formation and progression of atherosclerosis by down-regulating insulin receptor-mediated signaling pathways in vascular intima cells." (PMID 37773243, 2023). "Inactivation of the insulin receptor decreases mouse atherosclerosis lesions 6, which become more complex at later time points 6, suggesting that insulin resistance could have differential adaptive effects on CAS and atherosclerotic obstructive coronary artery disease." (PMID 34104095, 2021). "For novel atherosclerosis loci, 4 regions overlapped the most frequently across all stages of multi-trait analyses (nearest gene: BNC2, GPATCH2, INSR, JAZF1)." (PMID 40313769, 2025). "Hepatic insulin receptor knockout stimulates VLDL synthesis resulting in high blood triglyceride-rich lipoprotein levels and atherosclerosis." (PMID 26847458, 2016). "A study analyzing the human arterial tissue proteomics identified several vascular and plasma biomarkers related to early atherosclerosis including TNF-α, insulin receptor, PPARα, and PPARγ protein networks, predictors of both development and site of atherosclerosis and CVD." (PMID 31354915, 2019).
atherosclerosis (continued). "However, the role of insulin receptor (IR) isoforms, IGF-IR or insulin-like growth factor-II receptor (IGF-IIR) in VSMCs apoptosis during advanced atherosclerosis remains unclear." (PMID 29463262, 2018). "Interestingly, deletion of the insulin receptor specifically from macrophages, as opposed to whole body deletion, improves atherosclerosis on the Apoe-/- background." (PMID 26847458, 2016). "Moreover ApoE−/− mice with a heterozygous deletion of the IR and its downstream target, Insulin Receptor Substrate 1 (IRS1), also develop accelerated atherosclerosis, as well as mice lacking insulin receptor substrate 2 (IRS2−/−)." (PMID 28752048, 2017). "Additionally, the lack of insulin receptor gene and resulting attenuation of insulin signaling were shown to increase the expression of vascular cell adhesion molecule 1 (VCAM-1), a strong inducer of atherosclerosis, showing that loss of insulin signaling could accelerate atherosclerosis." (PMID 27247938, 2016).
Cognitive impairment (29 papers, 2008 to 2026). Abnormal cognition is characterized by deficits in thinking, reasoning, or remembering. "Insulin receptor desensitization in the brain is hypothesized to cause inhibition of insulin signaling pathway that ultimately causes cognitive deficits seen in SAD." (PMID 40108007, 2025). "Hence, many cognitive impairments associated with diabetes can also occur due to dysfunction of insulin receptor signaling cascades under hypoinsulinemia." (PMID 37025701, 2023). "However, impaired functions of IGF1 (insulin/insulin-like growth factor) signaling, which includes insulin receptor substrates, have been recognized as a risk factor for dementia and cognitive impairment." (PMID 32050523, 2020). "Therefore, altered insulin transport across the blood brain barrier as well as altered insulin receptor expression may explained the increased risk of developing cognitive impairment in patients suffering from primary headaches." (PMID 37721571, 2024). "Current evidence suggests that cognitive impairment in diabetic individuals may result from a mix of vascular and neurodegenerative damage, which can be influenced by deficiencies in intracellular signaling, mitochondrial metabolism, oxidative stress, and insulin receptor sensitivity." (PMID 37047011, 2023). "It is possible that JNK impairs insulin receptor signaling at multiple serine phosphorylation sites, which eventually promotes cognitive impairment induced by HFD." (PMID 25978724, 2015). "Furthermore, it was recently demonstrated that triglycerides can cross the BBB to directly induce hypothalamic leptin and insulin receptor resistance, leading to decreased satiety and cognitive impairment in mice." (PMID 30692905, 2018). "Soluble Aβ is a competitive inhibitor of insulin binding to the insulin receptor (IR), and increased levels of this Aβ could contribute to impaired insulin signalling and cognitive impairment in patients with AD." (PMID 27240327, 2016). "Future studies using insulin receptor knockout mice can help reveal the exact role of insulin receptor or insulin signaling in the anesthesia-induced cognitive impairment and whether or how much the neuroprotective role of intranasal insulin is through the insulin receptor." (PMID 28539885, 2017).
polycystic ovary syndrome (26 papers, 2013 to 2025). A disorder that manifests as multiple cysts on the ovaries. "The aim of this study was to assess the association between selected genetic polymorphisms (CYP19, MC4R, FTO, and INSR) and the clinical manifestations of polycystic ovary syndrome in Polish women." (PMID 40725495, 2025). "Analyses utilizing linkage and transmission disequilibrium tests on 150 families with affected individuals identified a variant near INSR that was significantly associated with PCOS or hyperandrogenemia, based on NIH criteria." (PMID 40889231, 2025). "The aim of this study was to investigate associations between INSR gene polymorphisms rs2059806 and rs2252673 with polycystic ovary syndrome." (PMID 40105555, 2025). "In clinically suspected patients with polycystic ovary syndrome, if there are extremely high blood levels of insulin in the blood, genetic testing should be performed to detect insulin receptor gene mutation of type A insulin resistance syndrome." (PMID 33728347, 2021). "Insulin and its receptor (INSR) have been implicated in the etiology of the polycystic ovarian syndrome (PCOS)." (PMID 33033446, 2020). "CYP17A1 is overexpressed in theca cells of women with PCOS, and its overexpression is driven by increased insulin receptor signaling, such that hyperinsulinemia can eventually cause hyperandrogenemia." (PMID 24717046, 2014). "In this section, we analyze the relationship between the occurrence of selected clinical symptoms of polycystic ovary syndrome and the presence of specific genetic polymorphisms in the CYP19, INSR, MC4R and FTO genes." (PMID 40725495, 2025). "This study aimed to evaluate the association between selected gene polymorphisms (CYP19, INSR, FTO, MC4R) and polycystic ovary syndrome in a group of Polish women." (PMID 40725495, 2025). "Commonly, patients with mild INSR defects present peripubertally with oligomenorrhea and hyperandrogenism and acanthosis nigricans; misdiagnosis with polycystic ovary syndrome has occurred." (PMID 32018348, 2020). "For instance, serine phosphorylation of the insulin receptor may induce hyperandrogenemia by upregulating P450c17 activity, the key enzyme in androgen biosynthesis, thereby increasing ovarian and adrenal androgen production." (PMID 40149685, 2025). "The analysis of the association between INSR gene variants rs1799817 and rs2059806 and the occurrence of clinical symptoms of polycystic ovary syndrome (PCOS) showed, in most cases, no significant statistical differences (p > 0.05)." (PMID 40725495, 2025). "In our participant, surgery was carried out very early; however, individuals with INSR defects can present peripubertally with features resembling polycystic ovary syndrome or adrenache and, if genetic testing is carried out in a timely manner, invasive measures can be avoided." (PMID 37897565, 2023). "In the present study, INSR exon 17 C/T SNP (rs1799817, His1058) did not increase the risk of polycystic ovary syndrome in North Indian Kashmiri women." (PMID 34912452, 2021). "The association of insulin resistance is significantly observed with polycystic ovary syndrome, so the use of drugs that increase the sensitivity of the insulin receptor, such as metformin and β-thiazolidinedione, has been considered in the treatment of these patients." (PMID 34404415, 2021). "Obese women with increased INSR expression in androgen-synthesizing ovarian cells may have hyperandrogenemia driven by the hyperinsulinemic response to reduced insulin receptor number in metabolic tissues." (PMID 26305227, 2015). "Vitamin D and insulin play an important role in susceptibility to polycystic ovary syndrome (PCOS), and therefore vitamin D receptor (VDR), parathyroid hormone (PTH), and insulin receptor (INSR) gene variants might be involved in the pathogenesis of PCOS." (PMID 27141540, 2015).
polycystic ovary syndrome (continued). "IR is a clinical feature of polycystic ovary syndrome (PCOS), possibly related to common factors controlling insulin receptor signaling, ovarian steroidogenesis and pituitary LH release." (PMID 37298967, 2023). "A transmission disequilibrium test (TDT) in affected siblings with hyperandrogenemia and PCOS-related traits predicted a strong association of follistatin, a nominal association of CYP11A1 gene, and a strong genetic association D19S884 allelic marker around INSR gene with PCOS." (PMID 34563259, 2021). "Similarly, aAb to the insulin-receptor may be involved as they can affect insulin signaling along with metabolic control of the reproductive axis, and rare cases of high aAb levels to the insulin receptor have been described in ovarian overgrowth and hyperandrogenemia." (PMID 33798258, 2021).
pancreatic cancer (25 papers, 2010 to 2024). "In pancreatic cancer, cannabinoids cause apoptosis by inhibiting pancreatic beta cell insulin receptor signaling, which interacts with the CB1 receptor from the MAPK and extracellular signal-regulated kinase (ERK) pathways." (PMID 36831374, 2023). "Here we report that in the context of hyperinsulinemic conditions [a common phenomenon in PDAC, either in the setting of new onset or long-standing diabetes], heparanase augments insulin-INSR signaling cascade in pancreatic tumor cells." (PMID 38078007, 2023). "Several of these were related to pancreatic function, including the insulin receptor recycling, cardiac myocyte insulin receptor signaling pathway, insulin signaling pathways, pancreatic cancer, and so on." (PMID 38000911, 2022). "High insulin receptor expression was found in pancreatic cancer tissue, and a high circular insulin level often predicts poor prognosis in PDA cases." (PMID 35252207, 2022). "When treated with an IGF-1 inhibitor, a compensatory insulin receptor (IR) overexpression was observed in pancreatic cancer cells." (PMID 35252207, 2022). "Many of them are relevant to pancreas functions, including insulin processing, insulin receptor recycling, insulin glucose pathway, pancreatic cancer, etc." (PMID 34489404, 2021). "Significantly, metformin inhibits the growth of human pancreatic cancer xenografts, possibly due to the ablation of the crosstalk among an insulin receptor (IR) and G protein-coupled receptors (GPCRs), in an AMPK-dependent manner." (PMID 27164115, 2016). "PGG acted as an insulin-mimetic compound that damaged pancreatic cancer cells (MiaPaCa2 and Panic-1) and alleviated cachexia in tumor-bearing mice by inhibiting insulin receptor/insulin-like growth factor receptor-1 activity and decreasing glycolytic enzymes in pancreatic cancer cells." (PMID 37375411, 2023). "Here we show that in PDAC elevated levels of heparanase, coupled with diabetic conditions typical for PDAC patients, promote growth and chemotherapy resistance of pancreatic carcinoma by favoring insulin receptor signaling and GLUT4-mediated glucose uptake into tumor cells." (PMID 38078007, 2023). "Furthermore, some cases out of a cohort of pancreatic cancer patients reveal coexpression of PD-L1 and the cytoplasmic insulin receptor in the tumor tissue as shown by immunohistochemistry." (PMID 34202040, 2021). "For example, CAFs produce an abundance of insulin-like growth factor 2 (IGF2) that renders cholangiocarcinoma and pancreatic cancer cells resistant to EGFR tyrosine kinase inhibitors (TKI) by activating the insulin receptor (IR)/insulin-like growth factor 1 receptor (IGF1R) signaling axis." (PMID 31067787, 2019). "In addition, the observation that human pancreatic cancer cell lines express insulin receptor and that the proliferation of these cell lines is induced by insulin also supports this conclusion." (PMID 25885700, 2015). "Our recent in vitro studies suggest that prolonged exposure of pancreatic cancer cells to mTOR inhibitors can promote insulin receptor substrate-PI3K interactions and paradoxically increase Akt phosphorylation and cyclin D1 expression in pancreatic cancer cells (negative feedback loop)." (PMID 20630061, 2010). "In pancreatic cancer, BMS-754807, a small-molecule inhibitor of the insulin-like growth factor-1 receptor/insulin receptor, improves gemcitabine responsiveness." (PMID 37284310, 2023). "Activation of insulin receptor (IR) and insulin-like growth factor-I receptor (IGF-IR) increases pancreatic cancer cell proliferation through activation of PI3K/mTOR and MAPK/ERK signaling pathway." (PMID 35893093, 2022). "Another paper reported that insulin receptor and G protein-coupled receptor cross-talk and activate YAP1 and TAZ in pancreatic cancer cells and that the activation is cancelled by PI3K inhibitor." (PMID 32267872, 2020).
pancreatic cancer (continued). "PGG were reported to antagonize insulin receptor/insulin-like growth factor-1 receptor (IR/IGF1R), hence sabotaging pancreatic cancer cells and ameliorating cancer cachexia." (PMID 33316951, 2020). "In parallel, metformin was shown to disrupt the crosstalk between insulin receptor and NTS receptor in pancreatic cancer cells." (PMID 25249538, 2014). "Metformin was shown to disrupt the crosstalk between insulin receptor and NTS receptor in pancreatic cancer cells." (PMID 25249545, 2014). "Besides induction of heparanase in pancreatic tumor cells due to PDAC-triggered impairment of glucose homeostasis, this connection involves heparanase-empowered activation of the INSR-AKT signaling cascade." (PMID 38078007, 2023).
type 1 diabetes (25 papers, 2010 to 2026). "Experimental studies in type 1 diabetes showed that C-peptide specifically bound to cell surfaces, acting via a G-protein-related receptor; it also led to autophosphorylation of the insulin receptor in the presence of insulin." (PMID 28228847, 2017). "Type 1 diabetes (T1DM) results from autoimmune destruction of pancreatic β-cells, whereas type 2 diabetes (T2DM) is primarily driven by insulin resistance and impaired insulin receptor signaling." (PMID 41463330, 2025). "MDCK II cells do not express the insulin receptor and therefore mimic proximal tube renal cells in type-I diabetes." (PMID 25056286, 2014).